IAPP (islet amyloid polypeptide)
Diseases named in the same sentence as IAPP in open-access papers (continued):
Sharing a sentence is not in itself a finding about the gene and the disease.
diabetes (continued). "Mouse models transgenic for human islet amyloid polypeptide (IAPP) allow for the studying of the importance of this polypeptide in the pathogenesis of diabetes." (PMID 37893225, 2023). "For AD, the main component of amyloid plaques is a specific βA, which is formed as a result of the targeted proteolysis of the APP, and, for diabetes, it is amylin (or islet amyloid polypeptide; IAPP), as well as insulin." (PMID 37833898, 2023). "In both models, GCK and IAPP methylation are found to be the major features contributing to the performance, highlighting their value as biomarkers in diabetes." (PMID 35207316, 2022). "In patients with diabetes and AD, there is misfolding and elevation of IAPP and accumulation of increased quantity of Aβ, tau hyper-phosphorylation." (PMID 35336756, 2022). "Marked downregulation of the Chr 14q32 locus miRNAs in the T2DM donor islets indicates a strong correlation between dysregulated IAPP expression and progression of diabetes pathogenesis, the mechanistic details of which need further experimental clarification." (PMID 35164285, 2022). "A number of studies have explored the link between diabetes and neurological pathology mediated via IAPP." (PMID 35475576, 2022). "In brief, our study uncovered urolithin B as a novel small molecule targeting IAPP pathological aggregation with potential to be exploited as a therapeutic tool for mitigating cellular dysfunction in diabetes." (PMID 36589826, 2022). "Animals where the human IAPP gene is highly expressed, develop diabetes as they grow during their lifetime." (PMID 35475576, 2022). "Autophagy was unveiled as one of the enriched pathways in the transcriptome of ppIAPP-expressing cells treated with urolithin B in accordance with the relevance of this pathway for IAPP toxicity and β-cell dysfunction in diabetes." (PMID 36589826, 2022). "Diabetes can lead to massive production of islet amyloid polypeptide (IAPP), which crosses the blood-brain barrier and is deposited in the brain (hippocampus), further causing misfolding and aggregation of β-amyloid, resulting in cognitive impairment." (PMID 36341127, 2022). "Islet amyloid polypeptide (IAPP) is another major factor that contributes to pancreatic beta cell death in diabetes." (PMID 35454131, 2022). "Exploration of urolithin B as a promising small molecule to prevent IAPP proteotoxicity, with implications for diabetes, is still in its infancy." (PMID 36589826, 2022). "Further providing evidence of such deleterious mechanism in vivo, a recent article reveals that an autophagy enhancer ameliorated diabetes of h-IAPP transgenic mice through clearance of amyloidogenic oligomers." (PMID 34069914, 2021). "The current perspectives, however, push forward the soluble IAPP oligomers and protofibrils as the main cytotoxic effectors of β-cell depletion and diabetes onset." (PMID 34959837, 2021). "Amylin (IAPP) is being increasingly viewed as a “second amyloid” with its identification in AD brains and particularly those AD patients with a history of diabetes mellitus." (PMID 34312771, 2021). "Diabetes has been considered to be a protein misfolding disease with islet amyloid polypeptide (IAPP) contributing to β-cell dysfunction and disease." (PMID 34426634, 2021). "The link between hIAPP and T2DM has been well established by studies demonstrating that IAPP aggregates are detectable in most diabetics and a spatial correlation exists between IAPP deposits and loss of β-cell mass." (PMID 33467592, 2021). "Under pre-diabetes and diabetes scenarios, the high demand for insulin production is accompanied by an increase in IAPP expression." (PMID 34959837, 2021). "In patients with PDAC and diabetes, increased serum glucagon, somatostatin and islet amyloid polypeptide (IAPP) levels were found to revert to normal following tumour resection, indicating an influence of tumour cells on the profiles of these hormones." (PMID 34680372, 2021).
diabetes (continued). "Pancreatic amyloid plaques of IAPP have been found in about 90% of individuals with diabetes, mainly as extracellular deposits in the vicinity of β-cells." (PMID 34959837, 2021). "Since such aggregates are implicate in pancreatic β-islet cell death, inhibition of IAPP aggregation is important in prevention of diabetes or of its progression." (PMID 33494628, 2021). "Although it is agreed that amyloid aggregation processes result in injury of β-cells, the precise cytotoxic mechanisms by which IAPP contributes to diabetes progression and exacerbation remains to be fully elucidated." (PMID 34959837, 2021). "Like Aβ deposition in AD, IAPP is also aggregated in people with diabetes to form pancreatic islet amyloid, and its detection in brain tissue has been linked with cognitive decline." (PMID 32503113, 2020). "Given these links, we have reviewed the mechanisms of IAPP dysfunction in diabetes and dementia, particularly in AD, thus adding to the recent view of multi-factorial contributions to both diseases." (PMID 32265649, 2020). "An earlier study concerning IAPP, an amyloidogenic peptide involved in diabetes, showed that insertion of this peptide into biological membranes is driven by free lipids." (PMID 33114222, 2020). "In a pre-diabetes/diabetes phenotypes, the increased production of insulin is accompanied by augmented IAPP levels." (PMID 32265649, 2020). "In diabetes, the islet amyloid polypeptide (IAPP or amylin) is found to be heavily glycated and to form toxic amyloid-like aggregates, similar to those observed for the Aβ peptides, often also heavily glycated, observed in Alzheimer patients." (PMID 32582762, 2020). "The relevance of IAPP proteotoxicity for diabetes pathophysiology and the potential reversibility of oligomers formation make IAPP an attractive target for the design of novel prophylactic, therapeutic, and diagnostic strategies." (PMID 33013747, 2020). "Here, we have first provided a brief perspective on the IAPP amyloidogenic process and its role in diabetes and AD." (PMID 32265649, 2020). "Misfolded IAPP can be formed and deposited in the brain of diabetes and AD patients, whereas Aβ and tau proteins can be detected in pancreatic islets in diabetes." (PMID 32503113, 2020). "Oxidative stress is known to be an important component of diabetes IAPP also induces decreases in protein transport and localization." (PMID 30419808, 2018). "We conclude that p300 is downregulated in an animal model prone to develop diabetes, due at least in part to the propensity of h-IAPP to form toxic oligomers." (PMID 29789539, 2018). "The accumulation of IAPP occurs only in human diabetes, thus suggesting that the role of autophagy in human diabetes would be better than in murine diabetes." (PMID 30249977, 2018). "A link between diabetes mellitus (DM) related islet amyloid polypeptide (IAPP) and Alzheimer’s disease (AD) related amyloid-β (Aβ) has been suggested in epidemiological and clinical studies." (PMID 28582864, 2017). "hAtg mice with β-cell specific IAPP expression replicate the T2D phenotype of islet changes to develop diabetes, with rutin treatment shown to prolong the onset of diabetes and ameliorate the severity of diabetic syndrome in treated mice." (PMID 28754022, 2017). "IAPP is not only a target relevant to the pathology of diabetes but also an exemplar of intrinsically disordered proteins (IDPs) and peptide subdomains of larger systems." (PMID 27108700, 2016). "The possible role of IAPP aggregation in the complications of diabetes has yet to be fully defined and the potential role of IAPP in type-1 diabetes remains to be elucidated." (PMID 26649319, 2016). "Islet amyloidosis by IAPP contributes to pancreatic β-cell death in diabetes, but the nature of toxic IAPP species remains elusive." (PMID 27213520, 2016).
diabetes (continued). "Amylin (islet amyloid polypeptide) and amyloid-beta (Aβ) protein, which are deposited within pancreatic islets of diabetics and brains of Alzheimer’s patients respectively, share many biophysical and physiological properties." (PMID 23966942, 2013). "Nevertheless,transgenic mouse models that express human IAPP develop fibrillar deposits andexhibit signs of diabetes." (PMID 18483616, 2008). "Mounting studies have demonstrated that macroautophagy maintains β cell function in cellular stress linked to T2DM, found in lipo- and glucotoxicity models, Endoplasmic Reticulum (ER) stress induced diabetes and human islet amyloid polypeptide induced diabetes." (PMID 39996055, 2025). "Considering the decrease in IAPP levels during diabetes advancement, it was explored the effects of IAPP in PDAC were explored to assess whether the loss of IAPP in diabetes could elevate the risk of pancreatic cancer." (PMID 39596226, 2024). "It was concluded that IAPP does not act as a tumor suppressor, indicating that the absence of IAPP signaling is unlikely to raise the risk of pancreatic cancer in individuals with diabetes." (PMID 39596226, 2024). "The overproduction of IAPP, which can induce insulin resistance, may play a role in the development of diabetes in these individuals." (PMID 39596226, 2024). "Furthermore, diabetes can be induced in these animals by transgenic modification to express human IAPP (hIAPP)." (PMID 39012029, 2024). "IAPP is involved in diabetes, Alzheimer’s disease and cardiovascular diseases." (PMID 37361541, 2023). "The HIP rat model (rats transgenic for human IAPP) is an exemplar that recapitulates the development of diabetes starting from a non-diabetic state at 2 months, impaired fasting glucose at 5 months, and diabetes at 10 months." (PMID 35475576, 2022). "In this way, the effectiveness of the molecules to inhibit aggregation and sustain cell viability could be investigated in a cellular milieu comprising a blend of immature and mature IAPP forms, mimicking what happens in vivo in the context of diabetes." (PMID 36589826, 2022). "Amylin (IAPP), a gluco-modulatory hormone co-expressed with insulin by pancreatic β cells, is downregulated in both T1D and advanced T2D, while amylin agonists are considered novel therapeutic agents for treating diabetes." (PMID 35788821, 2022). "However, deletion of CHOP only partially prevents mice from h-IAPP-induced diabetes, suggesting that other molecular mechanisms are involved in h-IAPP toxicity." (PMID 34069914, 2021). "We have reported that autophagy is crucial for clearance of amyloidogenic human IAPP (hIAPP) oligomer, suggesting that an autophagy enhancer could be a therapeutic modality against human diabetes with amyloid accumulation." (PMID 33420039, 2021). "The role of IAPP is undeniably relevant in both diabetes and AD." (PMID 32265649, 2020). "It is now clear that direct brain microvascular injury, leading to white matter disease, is unequivocally originated by elevated IAPP levels in diabetes, further supporting the “diabetes brain phenotype” hypothesis that we have proposed here." (PMID 32265649, 2020). "Here, we offer a brief appraisal of social impact and economic burden of these chronic diseases and provide insight into amyloidogenesis through considering recent advances of amyloid-β aggregates on diabetes pathology and islet amyloid polypeptide on Alzheimer’s disease." (PMID 32503113, 2020). "In the present paper, we sought to offer a brief overview of social impact and economic burden of these chronic diseases and provide insight into amyloidogenesis in light of recent advances of amyloid-β aggregates on diabetes pathology and islet amyloid polypeptide on AD." (PMID 32503113, 2020).
diabetes (continued). "Given that Islet Amyloid Polypeptide (hIAPP1–37) is the most abundant protein in amyloid fibres in the pancreas and its toxic oligomers are a crucial element in the physiopathology of Diabetes Mellitus, we have studied the hIAPP1–37 aggregation-oligomerization pathway." (PMID 29562662, 2018). "The IAPP amyloid oligomers are biomarkers of the onset and progression of diabetes and could play a role as therapeutic targets." (PMID 28912603, 2017). "Human islet amyloid polypeptide (hIAPP) aggregation is an early step in diabetes mellitus." (PMID 28912603, 2017). "On the other hand, IAPP hexamers could reflect the state of protein in the context of diabetes." (PMID 39859479, 2025). "However, we further detect it by recombinant proteins of these two peptides that people who have diabetes may have autoantibodies against sequences of IAPP and ZNT8 other than those found in the phage display system." (PMID 39483642, 2024). "IAPP has pleiotropic effects and is able to cross the blood–brain barrier, and hence there is potential for aggregation events occurring around the body that may contribute to the development of diabetes." (PMID 35455074, 2022). "Hence, the TXNIP/miR-124a/FoxA2/IAPP-signaling cascade represents a novel signaling branch in the β-cell that could be co-regulated by various stress factors related to diabetes." (PMID 35164285, 2022). "Currently, an FDA-approved analogue of human IAPP (containing several amino acid substitutions that prevent it from aggregation) named Pramlintide is prescribed for mealtime usage for patients affected from diabetes under insulin prescription in order to fulfil IAPP missing functions." (PMID 32131431, 2020). "Finally, we have proposed the concept of a “diabetes brain phenotype” hypothesis in AD, which may help design future IAPP-centered drug developmentstrategies against AD." (PMID 32265649, 2020). "In diabetes mellitus (DM), deposition of misfolded protein, i.e., islet amyloid polypeptide (IAPP), is observed in the pancreas." (PMID 28582864, 2017). "Moreover, transgenic mice expressing human IAPP develop hyperglycemia and diabetes." (PMID 25649462, 2015). "The role of IAPP aggregation in Diabetes Mellitus Type 2 (DM2) is well-established, but its implications in Diabetes Mellitus Type 1 (DM1) remain enigmatic." (PMID 39859479, 2025). "Two studies investigated the presence of natural oligomeric aggregates of IAPP (RIAO), one in the blood of 146 pediatric patients with obesity or diabetes, as well as 16 healthy children, and the other on healthy individuals, DM1 and DM2 patients." (PMID 39859479, 2025). "Other approaches focusing on liquid biopsy biomarkers for the management of diabetes have examined methylation of INS, IAPP and GCK either as single parameters or as combined parameters, i.e., INS and CHTOP in a duplex assay." (PMID 35207316, 2022). "In PDAC, the IAPP concentrations were 25.0 ± 8.7 pmol/L in seven patients with diabetes requiring insulin, 31.4 ± 12.6 pmol/L in 11 patients with diabetes not requiring insulin, and 12.2 ± 2.4 pmol/L in 9 patients with normal glucose tolerance." (PMID 39596226, 2024). "In the Tg2576 AD mouse model, IAPP plasma levels were not significantly elevated at an age where the mice exhibit the glucose intolerance of pre-diabetes." (PMID 37173803, 2023). "One of the most striking differences is amyloid deposition in pancreatic islets of >90% of T2D patients but not in those of murine diabetes, which is due to different amino acid sequences of amylin or islet amyloid polypeptide (IAPP)." (PMID 35237600, 2022). "This has been further corroborated in studies with transgenic rodent models, where rats that do not normally develop diabetes can become naturally diabetic if the human IAPP gene is inserted." (PMID 35455074, 2022). "In rodents, IAPP is nonamyloidogenic due to proline substitutions in the amyloidogenic sequence, and these species do not spontaneously develop diabetes." (PMID 34069914, 2021).
diabetes (continued). "Interestingly, thioredoxin-interacting protein (TXNIP) and islet amyloid polypeptide (IAPP) have also been shown to be up-regulated by glucose and diabetes and to be involved in β-cell apoptosis and inflammation." (PMID 27999212, 2017). "We used the mouse anti-IAPP antibody and the anti-amyloid oligomer antibody to study the temporal course of rIAPP oligomerization during STZ-induced diabetes using a wide array of methods, strategies and ideas derived from biochemistry, cell biology, and proteomic medicine." (PMID 28912603, 2017). "Immunization against toxic oligomers did not protect these mice from developing diabetes, indirectly suggesting that toxic IAPP oligomers originate and act intracellularly." (PMID 26582441, 2015). "Mice and rat IAPP do not aggregate, and these rodents do not normally develop diabetes." (PMID 35475576, 2022). "Since there is a considerable overlap in the changes in transcriptome in hIAPP and rIAPP mice, and hIAPP but not rIAPP mice develop diabetes, we next compared these transcriptomes to discern changes related to oligomer toxicity vs adaptation to an increased burden of IAPP expression." (PMID 34554282, 2022). "In the study of human pancreas from autopsies of Japanese showed that the deposition of IAPP increase with age, and the ratio of IAPP deposition for patients without diabetes but older than 70 years showed a significant increase (41.23%) compared with that for patients younger than 70 years (5.98%)." (PMID 33686020, 2021). "The relevance of exploring these two amyloids may not be stressed enough given that pancreatic IAPP aggregation has been found in over 96% of autopsied diabetes individuals, and Aβ plaques are constantly reported in the brain of the AD patients." (PMID 32503113, 2020). "This is illustrated by studies showing that IAPP deposition impairs brain function regardless of Aβ-42 pathology and that the brain of AD patients can also have IAPP deposits, alone or in the presence of Aβ-42, even if clinical signs of diabetes are absent." (PMID 32265649, 2020). "Pramlintide is administered in diabetes therapeutic and considered a non-aggregating peptide based on rat IAPP (rIAPP); however, this de novo design could not represent the best strategy." (PMID 29988450, 2018). "Here we wanted to investigate the level of naturally-ocurring or real (not synthetic) oligomeric aggregates of the human islet amyloid polypeptide (hIAPP) that we called RIAO in sera of pediatric patients with obesity and diabetes." (PMID 32833960, 2020).